GLS (glutaminase)
Diseases named in the same sentence as GLS in open-access papers (continued):
Sharing a sentence is not in itself a finding about the gene and the disease.
cancer (continued). "Genetic silencing or the inhibition of glutaminase (GLS) using the allosteric inhibitor BPTES decreases proliferation, induces cell death, and reduces proliferation in cancer cell lines as well as tumor growth in vivo." (PMID 35831624, 2022). "The primary target of this approach is the kidney isoform of glutaminase, glutaminase 1 (GLS1), a key enzyme in glutamine metabolism that is overexpressed in several human cancers." (PMID 36082022, 2022). "We found that the expression of PDHA1, GLS, DLAT, PDHB and MTF1 were differed between cancer and paracancer." (PMID 36620594, 2022). "The expressions of GLS and NQO1 were significantly higher in TCGA and ICGC cancer tissues, while IYD expression was significantly lower in HCC tissues compared with normal tissues." (PMID 36582227, 2022). "Cancer cells that upregulate xCT expression are particularly vulnerable to glutamine and glucose deprivation paving the way for the use of glutaminase and GLUT inhibitors in high xCT cancer cells." (PMID 36338517, 2022). "Upon inhibition of glutamine decomposition by GLS inhibitors (such as BPTES 21) or siRNA targeting GLS or GDH, mTORC1 activation can be blocked theoretically to inhibit the progression of cancer." (PMID 34604067, 2021). "For instance, a combination of glutaminase (GLS) inhibitor CB839 and 5-FU chemotherapy drug increases the anti-cancer effect on the xenograft growth of PIK3CA-mutant CRC cells without significant dose-limiting toxicity." (PMID 34887764, 2021). "Glutaminase isoenzymes GLS and GLS2 play apparently opposing roles in cancer: GLS acts as an oncoprotein, while GLS2 (GAB isoform) has context specific tumour suppressive activity." (PMID 33610185, 2021). "Mitochondrial enzymes, such as glutaminase (GLS), play a crucial role in the metabolism of glutamine and therefore represent highly regulated molecular switches in cancer." (PMID 34298698, 2021). "In many cancers, including RCC, anaplerosis of the TCA cycle is sustained via the conversion of glutamine to α-ketoglutarate, the first step of which is mediated by GLS." (PMID 34731180, 2021). "Glutaminolysis is a process of degrading glutamine catalyzed by glutaminase (GLS), and this process is essential for generating energy in various cancer types." (PMID 33567690, 2021). "In this study, we systematically analyzed the gene expression, epigenetic regulation, and genomic alterations of six key GLNM regulators (including SLC1A5, SLC7A5, SLC3A2, SLC7A11, GLS, and GLS2) across 33 different cancer types." (PMID 34573287, 2021). "In this cancer, CAF-derived Gln was exported to the tumor cells and converted to glutamate by the enzyme glutaminase." (PMID 33540679, 2021). "The importance of glutamine for cancer cell metabolism and survival is proved by successful clinical application of CBT-839, the inhibitor of glutaminase (GLS), which “enters” glutamine to open cancer metabolism." (PMID 33673109, 2021). "Glutaminase isoenzymes are related to the expression of some miRNAs and may contribute to either tumour progression or suppression through certain miRNA-mediated pathways, proving to be a key tool to switch cancer proliferation and redox status leading to a less malignant phenotype." (PMID 33610185, 2021). "The dependence of cancer cells survival on glutamine has led to testing of transport inhibitors targeting ASCT2 and the glutaminase (GLS) inhibitors, CB-839 and BPTES, for anticancer therapies." (PMID 34631530, 2021). "It has thus been shown that the inhibition of glutaminase and GDH1 by small molecules leads to a decreased viability of cancer cells in vivo and in vitro." (PMID 35010191, 2021). "The newly identified glutaminase (GLSs) inhibitors selenadiazole-derivatives CPD20 and CPD23 exhibited accumulated uptake in tumor cells and improved anti-cancer activity in CRC cells." (PMID 34200820, 2021).
cancer (continued). "The G-allele of the CCAT2 rs6983267 SNP has also been reported to preferentially bind the CFIm25 subunit of the cleavage factor I (CFIm) complex and promote alternative splicing of Glutaminase (GLS) mRNA, to promote cancer cell metabolism and proliferation." (PMID 33329688, 2020). "GLS isozymes have been consistently related to cell proliferation, but the role of GLS2 in cancer remains poorly understood." (PMID 32042057, 2020). "Glutaminase (GLS), which catalyzes the transformation of glutamine to glutamate, is regarded as another critical enzyme in growth and proliferation of cancer cells." (PMID 33173435, 2020). "As glutamine enters the cells, it is catalyzed to glutamate by glutaminase (GLS), an enzyme that is overexpressed during cancer growth." (PMID 32629884, 2020). "Of a number of BPTES-derived GLS inhibitors displaying much better drug-like properties compared to BPTES recently synthesized, only those already tested in cancer models will be presented below." (PMID 32880874, 2020). "xCT functionally couples to ASCT2 in cancer because ASCT2 can functionally provide glutamate by importing glutamine, which is converted to glutamate by a glutaminase (GLS) reaction." (PMID 32824193, 2020). "The application of glutaminase inhibitors attenuates the glutamine to glutamate conversion, elevates intracellular ROS level and impairs antioxidant GSH production in cancer cells." (PMID 33194749, 2020). "At all stages of OSCC cancer, ASCT2, GLS, and Ki‐67 protein levels were significantly increased compared with normal controls." (PMID 32162845, 2020). "The database was successively queried for GLS and GLS2 expression in all the cancers of interest and their respective normal tissues." (PMID 30871151, 2019). "In addition, BPTES was referred to inhibit only GLS1 and CB-839 was referred to inhibit both GLS 1 and 2 These results suggest a possible application of glutaminolysis inhibitors for EMT suppression in cancer cells with underlying molecular events by the treatment." (PMID 31027222, 2019). "To provide a systematic understanding regarding the role of GLS and GLS2 in cancer prognosis, we performed comparative data mining on numerous gene expression data sets." (PMID 30871151, 2019). "The varying prognostic characteristics of glutaminases suggest that GLS and GLS2 expression differentially modulate the clinical outcomes of cancers." (PMID 30871151, 2019). "Kidney-type glutaminase (GLS) and liver-type glutaminase (GLS2) are dysregulated in many cancers, making them appealing targets for cancer therapy." (PMID 30871151, 2019). "Our multiomics analysis revealed that GLS and GLS2 play distinct roles in cancer development and differentially modulate the clinical outcomes of cancer." (PMID 30871151, 2019). "In this regard, recent data have demonstrated that a potent TKI of EGFR, erlotinib, in combination with the glutaminase inhibitor CB-839 severely affects metabolic and energetic balances, leading to apoptotic death of NSCLC cancer cells." (PMID 31374910, 2019). "Cancers with MYC amplification exhibit elevated expression of amino acid transporters SLC1A5 and SLC38A5, as well as glutamine-metabolizing enzyme, GLS." (PMID 31627186, 2019). "To obtain further insights into the prognostic characteristics associated with glutaminases, we investigated the prognostic values of GLS and GLS2 expression levels for different types of cancer using the ProgonoScan database." (PMID 30871151, 2019). "The resulting gene expression patterns suggest that GLS and GLS2 are differentially expressed in cancer versus normal tissues and that the magnitude of their expression also varies depending on the tissue type." (PMID 30871151, 2019). "Microarrays identified glutaminase (GLS1), whose marked elevation in cancers has been observed as a downstream gene of HOTTIP." (PMID 28840253, 2018).
cancer (continued). "C-myc also regulates glutamine metabolism in cancer and stroma cells by inducing the expression of glutamine transporters (e.g., SLC5A1) and glutaminase 1 (GLS1, the initial enzyme of glutaminolysis)." (PMID 30151352, 2018). "Among the genes with the strongest reduction in expression we found hexokinase 2 (HK2) and glutaminase (GLS), which were both reported to be essential for energy generation to support proliferation in different cancer types." (PMID 28201987, 2017). "Glutaminase C (GAC) is the first and rate-limiting enzyme in glutaminolysis and plays important roles in cancer initiation and progression." (PMID 28039459, 2017). "In this process, glutaminase (GLS), which converts glutamine to glutamate, plays a key role in cancer cell metabolism, growth, and proliferation." (PMID 28522974, 2017). "Advanced development of glutamine starvation approach has been focusing on the specific glutaminase inhibitors, 968, BPTES and CB-839, in which the anti-cancer activity have been studied in vitro or in vivo." (PMID 28750681, 2017). "GLS1 has been reported to promote tumorigenesis in different types of cancer, including HCC, which is mainly attributable to its glutaminase activity and role in promoting glutamine metabolism." (PMID 26751560, 2016). "In addition, our findings that cancer cells acquire resistance to CB-839-inhibition by becoming auxotrophic for asparagine suggest that coupling GLS inhibition with an asparagine-low diet may improve efficacy of GLS inhibitors." (PMID 27126896, 2016). "Transcriptionally, c-Myc, which is often deregulated in cancer, induces the transcription of glutamine transporters SLC38A5 and SLC1A5 and upregulates expression of GLS, via its silencing of mir23a/b expression." (PMID 26425657, 2015). "As targeting glutaminase activity has been shown to inhibit oncogenic transformation, this study and others suggest GLS1 as a potential target for cancer therapy." (PMID 25844758, 2015). "Accompanied by increased glutamine consumption in most cancer cells, e.g., triple negative breast cancer cell MX-1, neuroblastoma cell and human myeloid cell KU812F, GLS activity is also much higher than normal cells." (PMID 26402672, 2015). "Glutamine is catabolized to glutamate by glutaminase (GLS) and incorporated into citric acid cycle and lipogenesis as an important energy source for proliferation of cancer cells." (PMID 25153931, 2014). "Cancer cells also have altered means to replenish the TCA cycle, for instance via pyruvate carboxylase (PC) or enhanced levels of glutaminase (GLS) driven by Myc expression." (PMID 25250177, 2014). "One enzyme in particular, glutaminase, localizes to the mitochondria and appears to be critical for entry of glutamine carbon into the tricarboxylic acid (TCA) cycle in many cancer cells." (PMID 25502225, 2014). "Our findings demonstrate amino acid sequences for selective inhibition of glutaminase isozymes and validate GLS2 as a potential anti-cancer target." (PMID 25026281, 2014). "We will now consider some of the outstanding questions regarding the regulation of glutaminase activity in cancer cells, and how intervention at the level of this enzyme and glutamine metabolism might offer new avenues for therapeutic intervention against cancer." (PMID 21234284, 2010). "Another GLS1 inhibitor, IPN60090 (IACS-6274), was tested in patients with advanced solid tumors (NCT05039801), and a blocker of “kidney-type” glutaminase, bis-2-(5-phenylacetamido-1,2,4-thiadiazol-2-yl)ethyl sulfide (BPTES), inhibited the cancer growth in P493 tumor xenografts." (PMID 40723225, 2025). "Furthermore, studies indicate that simultaneous inhibition of GLS and PHGDH, a critical enzyme in the serine/glycine metabolic pathway, can synergistically eliminate cancer stem cells." (PMID 41462613, 2025).
cancer (continued). "Through the action of glutaminase (GLS), glutamine is converted to glutamate, which is further metabolized into α- Ketoglutaric acid (α-KG) before entering the TCA cycle to provide energy and synthetic materials for cancer cells." (PMID 39744225, 2025). "Our study and others’ work suggest that multi-axis metabolic targeting (e.g., simultaneous inhibition of ASNS and glutaminase, or ASNS and autophagy) may provide synergistic benefit and prevent resistance by starving cancer cells of compensatory pathways." (PMID 41463097, 2025). "Our data demonstrate that the efficacy of erwinase resides in its glutaminase activity in PI3K-altered cancer cells, as kidrolase, another L-asparaginase lacking a robust affinity to glutamine, fails to demonstrate any cytotoxic effect." (PMID 40038309, 2025). "Thus, there is a potential therapeutic application in which the efficacy of other cancer treatments such as TMZ are increased because of the glutor and glutaminase inhibitor combination despite the nutrient-rich tumor microenvironment." (PMID 39329757, 2024). "Furthermore, mTORC1 not only regulates GLUD, but also actively controls GLS through S6K1-dependent c-MYC, enhancing cancer cells' uptake of glutamine." (PMID 38459595, 2024). "On the other hand, we did find that 6% of tumors that formed in mice with GLS deletion in cancer cells of origin became necrotic, which we did not observe in animals with GLS activity." (PMID 39303037, 2024). "Stromal glutamine was then shuttled into PCa cells via the increased expression of the glutamine transporter SLC1A5 where it was converted to glutamate by glutaminase (GLS) to replenish the TCA cycle and support the energetic need of proliferating cancer cells." (PMID 39335188, 2024). "A recent study showed that ASP extract effectively reduced the activities of G6PD, LDHA, PKM2, c-Myc, and glutaminase in HepG2 cells, suggesting that ASP may inhibit glycolysis and glutamine metabolism in cancer cells." (PMID 39697544, 2024). "Considering the interconnected roles of GLS, SIRT5 and Pi in cancer growth, our hypothesis is that activation of SIRT5 and reduction in Pi could represent a valid antitumoral strategy." (PMID 37627630, 2023). "Dysregulated c-Myc in CAF upregulates GLS and SLC1A5, enhances both glycolysis and glutaminolysis, and increases the secretion of metabolic intermediates such as glutamate to feed neighboring cancer cells." (PMID 36768660, 2023). "However, in the glutamine metabolism pathway, the important metabolic enzyme glutaminase and OGDH both have a significant upward trend in ARV-infected cancer cell lines, and the overexpression of σA protein in cancer cells has the same trend." (PMID 36851737, 2023). "Expression of glutaminase 1 (GLS1) is frequently elevated in malignant cells as a result of their metabolic reprogramming, while arginase 1 (ARG1) is secreted from myeloid cells in patients with various cancer types." (PMID 36765849, 2023). "The correlation calculated for all paired samples (33 cancer types) revealed that of the 10 cuprotosis molecules, six (DLAT, DLD, MTF1, CDKN2A, GLS and FDX1) may be negatively regulated by many miRNAs." (PMID 36895378, 2023). "Several lines of evidence have shown that alterations in GLS, GDH, GOT2, and GPT2 might be necessary for glutamine metabolism remodeling in cancer." (PMID 37525297, 2023). "In cancer carbon metabolism pathways, the Warburg effect obviously appeared in HSCC; glycolysis-related gene HK, PKM, and LDHA were upregulated; and transporter genes GLS, SLC1A5, MCT4 and GLUT1 were upregulated." (PMID 36090994, 2022). "patients with high expression of CDKN2A, MTF1, and GLS had worse prognoses, suggesting that CDKN2A, MTF1, and GLS might promote the proliferation of cancer cells." (PMID 36159561, 2022).
cancer (continued). "In cancer cells, the rate-limiting enzyme for glutaminolysis is GLS, the mitochondrial enzyme responsible for the conversion of glutamine to glutamate, which can exist as one of two isoforms, GLS1 and GLS2." (PMID 36276057, 2022). "Furthermore, we compared the differential expressions of cuproptosis-related genes between OSCC tissues and para-cancer tissues and found that four genes (LIAS, PDHB, GLS, and CDKN2A) were differentially expressed." (PMID 35875097, 2022). "It is expected that phospholipid-GNR might result in dysregulation of enzymes necessary to convert glutamine to glutamate, including the two mitochondrial glutaminases (GLS and GLS2) and consequently could affect diverse functions in cancer cell metabolism." (PMID 33673519, 2021). "In this study, we aim to elucidate whether some miRNAs can be modulated either by inhibition of GLS or by overexpression of GAB, impacting the redox state of cancer cells and contributing to the alterations in the markers of oxidative stress." (PMID 33610185, 2021). "Due to the critical role of glutamine metabolism in ferroptosis, treated BCAT2 overexpression cancer cells with 6-diazo-5-oxo-L-norleucine (DON, glutaminase inhibitor) could abolish the protective effect of BCAT2 in ferroptotic cancer cell death." (PMID 33097833, 2021). "Our results demonstrated that, even in the absence of GLS activity, cancer cells maintain the capacity to metabolize glutamine through ASNS, which expression in these conditions is increased due to the reduction in αKG production." (PMID 34376668, 2021). "Researchers have also discovered that the inhibition of glutaminase only leads to the suppression of growing cancer cells, not the hypoxic cells." (PMID 34360829, 2021). "A high level of glutamine transporter (SLC1A5) and glutaminases (GLS), two key factors involved in the conversion of glutamine into glutamate supplying nitrogen for anaplerotic flux to TriCarboxylic Acid (TCA) cycle, was detected in c-myc driven cancers." (PMID 34663785, 2021). "Even though this phenomenon warrants investigation in the context of cancer, it may be hypothesized that drugs like Compound 968 may skew TAM polarization towards the M1 phenotype, adding up to the anti-tumorigenic effect of GLS targeting." (PMID 34771610, 2021). "Future studies might involve investigating the possibility that GLS silencing and/or GAB overexpression can show synergic effects in combination with miRNA targeting as a new therapeutic strategy against cancer." (PMID 33610185, 2021). "Several of these genes are related to cancer, including CD44, DST, GLS, GNAS, KIF1B and AHRR." (PMID 34086943, 2021). "Both effects could explain the higher efficacy of glutaminase inhibitors and alkylating agents in IDH mutant cancer, as well as the best prognosis to temozolomide treatments in IDH, mutated glioma." (PMID 34070384, 2021). "It is noteworthy that the inhibition of glutaminase by CB-839 as well as the addition of oxidants was found to decrease the endogenous glutamate content and to sensitize cancer cells to NEAA withdrawal, even in absence of alterations in the KEAP1/NRF2 pathway." (PMID 32443774, 2020). "Glutaminase is not regarded as a potential drug for cancer therapy, but, instead, as a druggable target." (PMID 33510635, 2020). "Accordingly, we observed significant suppression of cancer cell proliferation and colony formation ability when AMPK or GLS expression was knocked down or the activity was inhibited, and the suppression effect was much stronger in cells with TIGAR overexpression." (PMID 32206103, 2020). "Although GLS inhibitors show promise for the treatment of certain cancers characterized by GLS upregulation 23-27, historically they have not been suitable candidates for CNS glutamate pathology due to poor solubility and blood brain barrier penetration." (PMID 32483415, 2020).